CLDN3 (claudin 3)
Diseases named in the same sentence as CLDN3 in open-access papers (continued):
Sharing a sentence is not in itself a finding about the gene and the disease.
tumor (continued). "This was expected as oncogene-enriched subtype tumours exhibited more aggressive tumour growth and had an increased expression of gene mutations involved in cell proliferation (ERBB2, SLC44A4, EPCAM, CLDN3, and CLDN4), cell differentiation (ELF3 and GPX2), and mucin production (KRT20)." (PMID 36723696, 2023). "Further studies may reveal if claudin-3 is a potential target for improving the management of tumor progression and metastasis." (PMID 36261482, 2022). "Thus, functional assessment of tumor cell extrinsic roles for claudin-3 in tumor metastasis is unclear." (PMID 36261482, 2022). "Furthermore, we observed an increased number of lymphatic vessels in B16F10 transplantation tumor of claudin-3/− mice while the density of blood vessels remained unchanged." (PMID 36261482, 2022). "Others also study the association of claudin-3 and tumor progression without distinguishing the expression of the protein on tumor cells or stromal cells." (PMID 36261482, 2022). "Our results indicated that the tumor microenvironment could affect lymphangiogenesis in part through the downregulation of claudin-3." (PMID 36261482, 2022). "We were wondering whether tumor microenvironment contributed to the alteration of claudin-3 expression." (PMID 36261482, 2022). "Here, the role of claudin-3 in tumor-induced lymphangiogenesis is investigated." (PMID 36261482, 2022). "Interestingly, the expression of claudin-3 in lymphatic endothelial cells is down-regulated by vascular endothelial growth factor C that is often present in the tumor microenvironment." (PMID 36261482, 2022). "Claudin-3 (CLDN3) in LUSC tissues is related to tumour progression and represses epithelial–mesenchymal transition (EMT) via activation of the Wnt pathway; therefore, CLDN3 may be a candidate biomarker for the prognosis and treatment of LUSC." (PMID 34112123, 2021). "The study demonstrates selective toxicity in Cldn3/4 overexpressing PC cells by optCPE gene transfer, mediated by pore formation, activation of apoptotic/necrotic signaling in vitro, induction of necrosis and of bystander tumor cell killing in vivo." (PMID 34503203, 2021). "In this study, CLDN3 was highly expressed in CCA as in other tumor types, which suggests that overexpression of CLDN3 may be involved in cancer survival." (PMID 33441949, 2021). "In the next step we analysed whether CLDN3, PALS1 and PAR6 expression levels were associated with tumor grade." (PMID 34531452, 2021). "Similarly, decreased Cldn-3 levels in squamous cell lung carcinomas significantly correlate with tumor stage and disease recurrence." (PMID 33584695, 2020). "Therefore, selective targeting of tumor tissues is necessary for the safety of CLDN3-targeted therapy in clinical application." (PMID 31905631, 2019). "However, another study on colorectal adenocarcinoma cell line revealed that claudin-3 overexpression promotes tumor malignancy via EGFR/MEK/ERK and PI3K/Akt signaling." (PMID 31316506, 2019). "Altogether, the ability of h4G3 to specifically recognize CLDN3-positive tumor cells suggests that it could be applied to immunoconjugates and CAR immunotherapy." (PMID 31905631, 2019). "A positive correlation was observed between CLDN3 with tumor grade and CK5." (PMID 31307407, 2019). "Imaging of C-CPE binding to tumor cells confirmed that the protein is capable to specifically target its receptors claudin-3, -4 and -7 expressed in the relevant tumor cells and demonstrated that the functionalization did not alter the binding capacity to the claudins." (PMID 30297847, 2018). "This could explain the expression of adherens and tight junction proteins such as VE-cadherin and claudin 3 in some metastatic tumor cells." (PMID 29844613, 2018). "However, information about the regulation of claudin-3 in the intestinal epithelium and tumor tissues is really limited." (PMID 28383479, 2017).
tumor (continued). "Consistent with this, by staining for a Claudin marker, Claudin 3, as well as an epithelial marker E-Cadherin, we found that these tumours were negative for both, suggesting a loss of their epithelial identity." (PMID 28194015, 2017). "The silencing CLDN3 expression in the ADC cells also decreased tumor growth in vivo." (PMID 28160565, 2017). "Overexpression of claudin-3 and 4 may lead to an increase in invasion, motility and tumor cell survival." (PMID 23822740, 2013). "We showed that knockdown of either CLDN3 or CLDN4 substantially increased tumor growth and metastases, which prompted us to postulate that these two claudins may function to suppress EMT." (PMID 23805314, 2013). "In contrast, the binding of CPE-containing toxins to CLDN3-knockdown cells was markedly reduced suggesting that the binding specificity is dependent on the expression of the claudin receptors on the tumor cell membrane." (PMID 21303546, 2011). "In contrast, negligible or no binding was detected by flow cytometry against LCL derived from the same patient from which OSPC-ARK-1 primary chemotherapy resistant tumor cell line was established or normal ovarian cells expressing low levels of claudin-3 and/or -4 (i.e., NOVA)." (PMID 20598131, 2010). "CLDN3 mRNA was present in all tumours and surrounding tissues." (PMID 15743508, 2005). "Moreover, CLDN3 downregulation in SqCC has been linked to EMT activation via the Wnt signaling pathway, suggesting its loss may drive tumor progression and dissemination." (PMID 40687428, 2025). "At the same time, the transcript levels of genes encoding for claudin-3 (CLDN3), the nuclear receptor subfamily 4 group A member 1 (NR4A1), and the transforming growth factor β (TGFB2) related to angiogenesis, hypoxic response and tumor invasion were up-regulated." (PMID 32664456, 2020). "Moreover, the genetic silencing of CLDN3 also reduce the tumor burden in vivo." (PMID 28160565, 2017). "One possibility is that CLDN3 is a transmembrane protein in the tight junction barrier, which may render its growth inhibition potential in vivo in response to extracellular signals originating from the tumor microenvironment." (PMID 25277196, 2014). "The fact that the CLDN3,4,7 cluster is present in both normal and tumors suggests that the mechanisms that lead to the coordinated expression of claudins in normal cells is conserved in tumor cells, although it may be inappropriately activated in cancer." (PMID 16836752, 2006). "Claudin-3 (CLDN3), which is up-regulated in GBM, also plays a role in promoting tumor cell growth and EMT via TGF-β signaling." (PMID 41141394, 2026). "This research highlights CLDN3 role in supporting GBM growth and metastasis, linking it to the tumor-promoting functions of TGF-β." (PMID 41399659, 2026). "The tumor area, the count of microscopic lesions and invaded bronchiolar spaces were determined based on CC10, SPC, and claudin-3 IHC stains, respectively." (PMID 40360735, 2025). "CD24, CLDN3, WFDC2, and TACSTD2 genes were present in all the tumour clusters of all samples, and the genes C1orf194, C20orf85, MS4A8, ODF3B, RSPH1, and TPPP3 appear to be co‐expressed." (PMID 41160707, 2025). "The use of in vitro and in vivo models has demonstrated that targeting CLDN1, CLDN3, CLDN4, CLDN6 and CLDN18.2 consistently reduces tumor burden across a multitude of different cancer types, with specific intra-tumoral accumulation and low rates of AEs." (PMID 38371623, 2024). "Low expression of CLDN3 was found to be correlated with positive lymphatic invasion, advanced tumor depth, and lower TNM stage, whereas overexpressed CLDN3 was related to lymph node metastasis." (PMID 37109309, 2023). "Based on our results, both the tumor conditional medium and VEGF-C are sufficient to downregulating the expression of claudin-3 on LEC, which further suppresses tumor lymphangiogenesis." (PMID 36261482, 2022).
tumor (continued). "Significant differences in CLDN3, CLDN4, CLDN5, CLDN6, CLDN9, CLDN11, and CLDN12 expression were evident as a function of tumor stage." (PMID 35281827, 2022). "The parameters analyzed were the size of the tumor, the proliferation index (Ki-67 expression), CD24, Claudin 3, and Claudin 4 expression." (PMID 34298771, 2021). "CLDN3 was reported as a positive regulator of cancer stemness in nonsquamous NSCLC and its depletion decreased the formation rates of spheres and tumours and increased cisplatin sensitivity." (PMID 33597819, 2021). "For BRCA2 versus BRCA1 tumors, univariate analysis showed that tumor grade, ER, PR, HER2, CK5, CK14, and CLDN3 were independent parameters of BRCA2 status." (PMID 31307407, 2019). "We further demonstrated the selective and efficient antitumoral action of CPE gene therapy in the claudin-3 and -4 overexpressing PDX Co7515, where gross tumor necrosis of the treated tumors was observed." (PMID 28193196, 2017). "Moreover, CLDN3 could significantly inhibit HCC tumor growth in vivo." (PMID 25277196, 2014). "Re-expression of E-cadherin in the CLDN3 or CLDN4 knockdown cells reduced migration, invasion and tumor growth in vivo." (PMID 23805314, 2013). "Down-regulation of E-cadherin, occludin, claudin 3, 4, 7 as well as up-regulation of the mesenchymal genes and SNAI2 is in line with the features described in claudin-low tumor samples." (PMID 22044755, 2011). "Notably, genes such as TFF3, CLDN3, CDH17, and REG4 exhibited specific expression in tumor cells, linking to the cancer progression." (PMID 40452847, 2025). "Certain tumor samples, however, especially in the MEC group showed high expression of CLDN3 and -4." (PMID 37621953, 2023). "CLDN3, CLDN4 and CLDN7 were expressed at an abnormally high level in tumor cells and IM cells." (PMID 35999201, 2022). "For instance, GBC9-MT showed elevated expression of CD24 (immune checkpoint in promoting immune evasion) and IGFBP2 (metabolic checkpoint in promoting tumor growth), and GBC10-MT displayed cancer stem cell signature (OLFM4) and enhanced cell migration (e.g., CLDN3, CEACAM5)." (PMID 36198671, 2022). "By immunofluorescence staining of the tumor tissues, we could see co-expression areas of LYVE-1 positive and claudin-3 positive staining in claudin-3+/+ mice." (PMID 36261482, 2022). "The primary tumor volume between claudin-3−/− and claudin-3+/+ mice showed no statistical difference." (PMID 36261482, 2022). "In the Cldn3/4 low expressing MIA PaCa-2/eGFP-Luc tumors non-viral optCPE gene transfer led to significant reduction of tumor viability (p = 0.0336) and tumor volume (p < 0.0001) compared to vector control (VC) treated mice." (PMID 34503203, 2021). "Claudin 3 expression has been demonstrated in 79% of ER negative tumours and 89% of ER positive tumours." (PMID 31044387, 2020). "Genes other than CLDN1, CLDN3, CLDN4, CLDN7, and ZO1 may also be coordinately regulated by DOCK1 and may contribute to tumor growth, but this remains to be investigated." (PMID 31717460, 2019). "Since, claudin-3, -4 or -7, the CPE receptors, can be upregulated in tumor cells, the use of C-CPE-AuNP could be a promising technique for a specific cancer therapy." (PMID 30297847, 2018). "Further studies evaluating CLDN expression in different tumour types reported a decrease or lack of CLDN-3, -4 and -7 expressions of in vitro cultured cells compared to uncultured cells." (PMID 27690019, 2016). "We confirmed that three of these candidates (CDH11, ICAM1 and CLDN3) were overexpressed in tumors when compared to normal esophagus, normal gastric and non-dysplastic Barrett's, and localized to the surface of tumor cells." (PMID 27363029, 2016). "We next screened by flow cytometry this panel of cell tumour phenotypes with epithelial markers (EpCAM, E-cadherin, Muc1, claudin-3 andclaudin-4) or non-epithelial markers (N-cadherin, vimentin, CD66, EGFR, FGFR, EphB4,ALDH1 and CD49f)." (PMID 27711186, 2016).
tumor (continued). "Ectopic expression of CLDN3 in HCC cells could inhibit cell motility, cell invasiveness, and tumor formation in nude mice." (PMID 25277196, 2014). "CLDN3 exhibited no expressional difference between invasive tumours and nontumourous tissue samples." (PMID 15743508, 2005). "There were no remarkable differences in CLDN3 expression in different types of breast lesions or between normal and tumour components." (PMID 15743508, 2005). "However, this does not dispel all doubts that there could be pre‐tumour cells in control 3, supported by the presence of CLDN3 and WFDC2 which are two markers always present in tumour clusters." (PMID 41160707, 2025). "Therefore, CLDN3 expression was analyzed in more than 14,500 tumor tissue samples from 133 different tumor types and subtypes as well as 76 non-neoplastic tissue categories by IHC in a tissue microarray (TMA) format in this study." (PMID 39658782, 2024). "Both the healthy and tumor epithelium from the oral cavity did not express the claudin-3 protein." (PMID 36232536, 2022). "Hepatic expression of claudin-4 is low, compared with tumor, although claudin-3 expression is not insignificant and may play a role in the differences we have observed." (PMID 32414951, 2020). "Notably, overexpression of CLDN3 did not affect cell proliferation in vitro but inhibit tumor growth in vivo." (PMID 25277196, 2014). "Claudin-3 and -4 genes have been reported to be highly differentially expressed in biologically aggressive malignancies including ovarian serous carcinoma (OSC) and the identification of claudin protein expression has proven to be of clinical relevance in this tumor and a variety of others." (PMID 23685873, 2013). "Furthermore, endoscopic guided laser ablation in combination of pre-treated C-CPE-AuNP tumors could be a strategy to specific combat chemo-resistant tumor types overexpressing the C-CPE receptor claudin-3 and -4 without adverse side effects." (PMID 30297847, 2018). "Reduced expression of CLDN4, but not CLDN3, led to remarkable decreases of cytotoxicity, and the injection of CPE around PC3 xenografts significantly suppressed tumor growth." (PMID 37621953, 2023). "The h4G3 was highly specific for CLDN3—not for other CLDN family members—showed ADCC activity depending on CLDN3 expression, and preferentially accumulated in tumor tissues over normal tissues." (PMID 31905631, 2019).
cancer (85 papers, 2006 to 2025). A tumor composed of atypical neoplastic, often pleomorphic cells that invade other tissues. "These toxins aid in the treatment by disrupting the osmotic balance of cells and causing cancer cell death by binding to the Claudin-3 and -4 surface receptors, which are abundantly present in cancer cells." (PMID 39467702, 2024). "The dysregulation of CLDN3 has been implicated in cancer and inflammatory diseases." (PMID 41200201, 2025). "Functional studies on cell line models identified associations between reduced CLDN3 expression and various cancer driving mechanisms such as a decrease in epithelial barrier function, invasiveness, dedifferentiation, proliferative potential, and reduced adhesion." (PMID 39658782, 2024). "Claudin-low cancer represents a rare and biologically aggressive variant of epithelial tumor A claudin-low molecular subtype of breast cancer has been described as having low expression of claudin-3, -4, and -7 and E-cadherin, with concomitant stem cell features." (PMID 34354941, 2021). "In the spectrum of 33 human cancer types, CLDN3 demonstrates an expression pattern that closely mirrors EpCAM’s." (PMID 40057807, 2025). "Then, we used these monovalent format antibodies against EpCAM or CLDN3 to test their binding and internalization activity in OVCAR-3 and NCI-H1781 cancer cells, ultimately obtaining five EpCAM antibodies and three CLDN3 antibodies that met the requirements." (PMID 40057807, 2025). "CLDN3 is highly expressed in multiple human cancers such as ovarian, breast, prostate, and pancreatic cancers." (PMID 40057807, 2025). "Other claudin family members besides CLDN1, CLDN3, CLDN4, CLDN6 and CLDN18.2 have also been implicated in various stages of cancer progression, including metastasis." (PMID 38371623, 2024). "Several of these studies have found a link between either elevated or reduced CLDN3 expression levels and poor prognosis of cancer patients." (PMID 39658782, 2024). "The expression of CLDN3 in cancer has been analyzed in more than 45 studies using immunohistochemistry (IHC)." (PMID 39658782, 2024). "CLDN3 is found upregulated in various cancer types, including ovarian, breast, colon, gastric, liver, and pancreatic cancer, and has been targeted in these contexts." (PMID 38371623, 2024). "Both demonstrated ADCC in vitro, where h4G3 had dose dependent activity across multiple cancer cell lines that correlated with the levels of CLDN3 expression on target cells." (PMID 38371623, 2024). "Claudin-3 was also shown to induce cancer stemness via estrogen receptor-α, thus acting as a proliferation activator." (PMID 36675266, 2023). "This raises the possibility that claudin 3 and 4 are potential therapeutic targets for these cancers from a clinical perspective." (PMID 36714681, 2023). "Comparing proteomics of the IFN-γ + INCB24360 group with other groups, we found that Claudin-3, a Zonula occludens, and inhibitor of carcinoma metastasis, was dramatically reduced in IFN-γ + INCB24360 and INCB24360 treated KPIC PDAC organoids." (PMID 36517670, 2023). "Claudin-3-overexpressing lung cancer cells were insensitive to cisplatin treatment, and targeting transcription with small molecules suppressed cancer stemness and reversed chemoresistance." (PMID 34354941, 2021). "Another report also revealed that claudin-3 inhibits cancer aggressiveness and is a potential prognostic biomarker for HCC." (PMID 34338154, 2021). "Although high expression of claudin-3 in cancer has been reported, few records of detailed values of sensitivity and specificity of biomarkers are available." (PMID 33441949, 2021). "We compared CLDN3 staining in surgical specimens obtained from normal bile duct epithelium and carcinoma (n = 5)." (PMID 33441949, 2021).